CCRL2 (C-C motif chemokine receptor like 2)
Diseases named in the same sentence as CCRL2 in open-access papers (continued):
Sharing a sentence is not in itself a finding about the gene and the disease.
cancer (11 papers, 2017 to 2025). A tumor composed of atypical neoplastic, often pleomorphic cells that invade other tissues. "In the present study, we analyzed the consequences of Ccrl2 loss of function in different mouse models of cancer, namely the DMBA/TPA chemical model of skin carcinogenesis and the B16 and LLC graft models." (PMID 34638484, 2021). "We observed that B16 and LLC tumors from Ccrl2-deficient mice displayed a significant downregulation of an angiogenesis signature of 38 genes described for a set of human cancer types." (PMID 34638484, 2021). "CCRL2 binds chemerin, a multifunctional protein with well-established functions in inflammation, cancer, adipogenesis, and glucose homeostasis, with high affinity without inducing receptor internalization or activating downstream signaling cascades." (PMID 40867595, 2025). "Previous studies have demonstrated that CCRL2 expression influences the clonogenic potential of various cancer cell lines." (PMID 40867595, 2025). "CCRL2 expression was described in different cancer cells, including prostate and breast carcinoma, colorectal cancer liver metastasis and glioblastoma." (PMID 33363177, 2020). "Other reports described CCRL2 expression in hepatic stellate cells, in adipocytes, in skin and in different cancer tissues including breast and prostate cancers." (PMID 33363177, 2020). "Recent studies have reported the expression of CCRL2 in different human cancer cell lines and tissues." (PMID 29497024, 2017). "CCRL2 has garnered attention for its regulatory functions in inflammation and cancer." (PMID 40867595, 2025). "Further studies in other cancer types and cell models are needed to determine whether CCRL2’s regulatory role is broadly conserved and to explore its potential as a therapeutic target in solid tumors." (PMID 40867595, 2025). "In the present work, we investigate the role played by CCRL2 in mouse cancer models." (PMID 34638484, 2021). "To illustrate the therapeutic potential of CCRL2 as a therapeutic target, we developed an anti-CCRL2 antibody-drug conjugate (ADC) by conjugating an anti-CCRL2 antibody with the cytotoxic drug pyrrolobenzodiazepine (PBD), which causes DNA double-strand breaks leading to cancer cell death." (PMID 41282192, 2025). "However, the functional role of CCRL2 in cancer has been investigated in few studies so far." (PMID 34638484, 2021). "However, the functional role of CCRL2 in cancer is still unknown and needs further investigations." (PMID 33363177, 2020). "While a role for CCRL2 in NKT cell cancer immunity has not been reported, our findings raise questions on the potential diversity of CCRL2 in regulating cell activation." (PMID 36662882, 2023). "The function and expression of CCRL2 in cancer are not understood at present." (PMID 29497024, 2017). "In cancer, however, the expression of CMKLR1, GPR1, and CCRL2 has not been studied to great extent." (PMID 35008289, 2021).
infection (9 papers, 2013 to 2025). The state of being infected such as from the introduction of a foreign agent such as serum, vaccine, antigenic substance or organism. "In CCRL2-mediated immune response, CCRL2 receptors are activated upon recognition of infection or other pathogen- or wound-associated stimuli, and in turn, promote immune response to bolster host resistance mechanisms." (PMID 37965346, 2023). "Analysis of macrophage‐related cytokines and chemokines found that Tnf, Il1b, Il1a, Ilrn, Il17ra, Cxcl1, Cxcl2, Ccrl2, Ccl3, Ccl4, and Ccl9 expression significantly increased over the course of infection." (PMID 41117166, 2025). "In fact, it has been reported that during an RSV (respiratory syncytial virus) infection, lung neutrophils are characterized by upregulation of CCRL2." (PMID 39811276, 2025). "The expressions of CCR5 (the receptor of CCL3, CCL4, and CCL5) and CCRL2 (expressed on neutrophils and primary monocytes) were significantly down-regulated by the WT infection." (PMID 37513744, 2023). "There was a robust correlation between SARS-CoV-2 transcripts and the IFN-γ-induced chemokine Cxcl-10 (IP-10) and to a lesser extent Csf1, Ccrl2, and Ccl5, which are all involved in the recruitment of immune cells to the site of infection." (PMID 34319784, 2021). "In particular, the significant over-expression of the Csf1, Lefty1, Ccrl2, Gdf3, Il-10 and Ccl8 genes (1.8–5.8 fold increases) was seen at day 9 post-infection." (PMID 23861742, 2013). "Of note, global deficiency of CCRL2 did not alter normal development and had no significant impact on blood counts or incidence of infection in mouse models." (PMID 40181978, 2025). "However, in response to infection, male mice exhibited higher expression levels of CXCL2 (KO, 1A3, and 6A2), SAMHD1 (1A0, 1A3), RSAD2, STAT1, and STAT3 (1A0), MYD88 and PSMB8 (1A3), BCL3, BCL10, CCRL2, IFITM2, RTP4, and ZFP36L1 (6A2), compared to females." (PMID 32670284, 2020).
adenocarcinoma (1 paper, 2024). A common cancer characterized by the presence of malignant glandular cells. "Prognostic analysis using the Kaplan–Meier Plotter revealed that higher expression of CSF3 and CCRL2, as well as lower expression of IL1A, were significantly associated with prolonged PPS in adenocarcinoma patients undergoing chemotherapy." (PMID 39727962, 2024).
bacterial infection (1 paper, 2025). "Analysis of proinflammatory cytokines and chemokines at different time points showed significant upregulation of Tnf, Mmp14, Il1b, Il1a, Il17ra, Cxcl1, Cxcl2, Ccrl2, Ccl3, Ccl4, and Ccl9 after bacterial infection." (PMID 41117166, 2025).
hematologic malignancies (1 paper, 2025). "This is consistent with prior studies showing CCRL2’s interaction with TLR4 in macrophages, enhancing its stability and supporting NF-κB activation, and its involvement in IFN-γ/STAT1 signaling in hematologic malignancies, even in the absence of exogenous cytokine." (PMID 40867595, 2025).
infectious disease (1 paper, 2013). A disorder directly resulting from the presence and activity of a microbial, viral, or parasitic agent in humans. "However, as noted, given the very high linkage between HHG*1 and a CCRL2 haplotype that has been shown to influence other infectious and non-infectious diseases, one cannot exclude a possible role for CCRL2 in HCV susceptibility." (PMID 23936229, 2013).
neurodegenerative disease (1 paper, 2023). A disorder of the central nervous system characterized by gradual and progressive loss of neural tissue and neurologic function. "Therefore, further research is needed on ACKR1–3 and CCRL2 in connection to neurodegenerative diseases." (PMID 38003682, 2023).
retinopathy (1 paper, 2021). "Pathological angiogenesis was also reduced in CCRL2-/- mice in a model of oxygen-induced retinopathy." (PMID 35004698, 2021).
CCRL2 also shares sentences with these, for which no sentence is quoted: Insulin resistance (2 papers); Pneumocystis pneumonia (2); acute erythroid leukemia (1); airway hyperresponsiveness (1); atopic allergy (1); atopic asthma (1); autoimmune disease (1); autoimmune myocarditis (1); benign prostatic hyperplasia (1); Cachexia (1); cardiac hypertrophy (1); cervical carcinoma (1); Cognitive impairment (1); cutaneous squamous cell carcinoma (1); gastric cancer (1); heart failure (1); hepatocellular carcinoma (1); hookworm infection (1); leukemia (1); Lewis lung carcinoma (1); lung adenocarcinoma (1); lung disease (1); mastitis (1); metabolic disease (1); myeloid neoplasm (1); neurofibroma (1); non-small cell lung carcinoma (1); pneumonia (1); prostate tumors (1); rhinitis (1).
A further 4 diseases each share a sentence with CCRL2 in 1 paper.